APOC1 (apolipoprotein C1)
Diseases named in the same sentence as APOC1 in open-access papers (continued):
Sharing a sentence is not in itself a finding about the gene and the disease.
tumor (continued). "The results from the GEPIA database revealed that the APOC1 level was significantly increased in tumor tissues compared to that in normal tissues." (PMID 32974161, 2020). "APOC1 expression was much higher in ccRCC tumor tissues, and high expression of APOC1 correlated with a shorter OS, PFS, and poor clinical characters, including cancer stage, tumor grade, and tumor size." (PMID 32974161, 2020). "The expression of APOC1 was found to be significantly correlated with the tumor size (p = 0.018) and histological grade (p = 0.016)." (PMID 32974161, 2020). "We compared the expression level of APOC1 in the urinary tumor tissues and normal tissues using databases and found a general higher expression in tumors as compared to that in normal tissues." (PMID 32974161, 2020). "Further research should be undertaken to uncover the potential mechanism of APOC1 promoting ccRCC tumor progression by regulating cholesterol metabolism." (PMID 32974161, 2020). "The transcriptional expression of APOC1 in tumor tissues was significantly higher than that in the adjacent tissues (p < 0.01)." (PMID 32974161, 2020). "Knockdown of APOC1 expression significantly suppressed proliferation of tumor cells and decreased colony formation, whereas overexpression of APOC1 increased growth of THP1 and HL60 cells." (PMID 31573738, 2019). "Notably, FCGR1A, CD14, and APOC1 emerged as key features within the model, with APOC1 also serving as a prominent marker for tumor-enriched macrophage subtypes." (PMID 41601657, 2026). "Similarly, in vivo studies demonstrated that APOC1 knockdown significantly reduced tumor growth, angiogenesis-related proteins, and phosphorylated PI3K/AKT/mTOR pathway proteins in nude mice." (PMID 39873475, 2025). "Similarly, Transwell assays demonstrated that APOC1-silenced TAMs suppressed the invasion capability of the tumor cells." (PMID 39877420, 2024). "Furthermore, results from EdU proliferation assays indicated that, compared to the control group, APOC1-silenced TAMs effectively slowed down the proliferation of tumor cells." (PMID 39877420, 2024). "Furthermore, APOE, APOC1, C1QA, C1QB, and NUPR1 are indicative markers of variations in the infiltration of tumor-associated macrophages (TAM), where TAM infiltration is known to be associated with unfavorable survival outcomes in solid tumors." (PMID 38783355, 2024). "Thus, APOC1+ TAMs facilitate the construction of tumor tolerance environment by modulating lipid metabolism." (PMID 39232806, 2024). "Further investigation into the function of APOC1 within the tumor immune microenvironment could provide valuable insights into the mechanisms underlying cancer progression and offer novel therapeutic opportunities." (PMID 39877420, 2024). "The role and mechanism of APOC1 in the tumor microenvironment have only been partially studied." (PMID 36908705, 2023). "The analysis showed that APOC1 mRNA expression was significantly upregulated in ESCA tissues compared with normal tissues (p < 0.001), and the expression of APOC1 mRNA was also significantly increased in ESCA tissues compared with tumor adjacent tissues (p < 0.01)." (PMID 36969562, 2023). "Our results showed that tumor targeting-related immune checkpoint genes such as CD274 (p = 0.0137), TGFB1 (p = 0.0175), PDCD1 (p < 0.001), CTLA4 (p < 0.001), and LAG3 (p < 0.001) were significantly associated with APOC1." (PMID 36969562, 2023). "We also analyzed APOC1 expression in various tumor tissues and tumor-adjacent tissues." (PMID 36969562, 2023). "Furthermore, based on the crosstalk analysis in this study, we identified that APOC1+APOE+ macrophages were involved in the establishing of the metastatic immune microenvironment by interacting with tumor and stromal cell." (PMID 36709495, 2023). "In addition, the spatial characterization of APOE+ APOC1+ macrophages in microenvironment of primary tumor and metastatic lymph node were evaluated by multiplex IF staining." (PMID 36709495, 2023).
tumor (continued). "Related studies have also shown that APOC1 may influence tumor progression in patients with kidney cancer and colon cancer by regulating gene expression and may be a potential prognostic marker for tumors such as gastric cancer and lung cancer." (PMID 36969562, 2023). "Our results point to the hypothesis that increased ApoC1 values correspond to a higher tumor burden." (PMID 36101402, 2022). "Theoretically, due to the tumor-induced damage of the blood brain barrier, and after neurosurgically provoked local disruption, ApoC1 may be swept into the blood stream and consecutively lead to measurable changes of ApoC1 serum levels." (PMID 36216850, 2022). "Distinctive from ApoC1, ApoB and ApoA1 seem to be tumor suppressors in RCC." (PMID 36506554, 2022). "In general, we observed APOC1, APOE, C1QB and NURP1, which may reflect differential abundance of tumor-associated infiltration of macrophages (TAM)." (PMID 36250636, 2022). "Recent literature documents the role of APOC1 in several in vitro and in vivo tumor models." (PMID 34298684, 2021). "Moreover, the cluster of EpCAM enriched cells were also enriched for several other genes of clinical interest including APOC1, a biomarker of tumor progression, ALDH1A1, a marker of tumor cell “stemness”, and AKR1C3, a marker of doxorubicin resistance." (PMID 33989287, 2021). "Apolipoprotein C1 (APOC1) has been identified as a vital regulator in tumor progression." (PMID 33430855, 2021). "We further investigated the role of APOC1 in the tumor progression of ccRCC and KIRP." (PMID 32974161, 2020). "The western blot analysis revealed that higher protein expression of APOC1 could be found in patients of ccRCC with higher tumor grade." (PMID 32974161, 2020). "Further evidence on the mechanism of APOC1 promoting tumor progression may transform it to a new therapeutic target for the treatment of ccRCC." (PMID 32974161, 2020). "According to the function related to inflammation, angiogenesis, apoptosis, fibrosis and tumor growth, which are closely associated with either the development of DR or VEGF signaling, we were interested in following candidate proteins: APOC1, SERPINA5, TIMP2, and KRT1." (PMID 29541006, 2018). "However, the mechanisms of APOC1 in tumorigenesis, progression, and metastasis, particularly in tumor immune regulation, remain unclear." (PMID 39877420, 2024). "This may be because the TME with high APOC1 expression affects the polarization of macrophages, causing macrophages to secrete substances such as IL10, which in turn causes pro-tumorigenic effects of macrophages on ESCA cells, leading to tumor development." (PMID 36969562, 2023). "Because APOC1 has a close relationship with both tumor internal factors and tumor external factors of the tumor immune microenvironment (TIME), we hypothesized that the expression level of APOC1 may be a potential predictive biomarker for application as an immune checkpoint inhibitor." (PMID 36969562, 2023). "Hence, we suggested that APOC1 might affect tumour malignancy and cancer prognosis by regulating T cell exhaustion and macrophage polarisation." (PMID 34498424, 2021). "We speculate that APOC1 might act as a tumor promoter by regulating the cholesterol metabolism." (PMID 32974161, 2020). "Furthermore, higher expression of APOC1 was observed in higher tumor grade of KIRC." (PMID 32974161, 2020). "Similarly, the APOC1 protein level was also found to be higher in tumor tissues." (PMID 32974161, 2020). "Furthermore, genes previously associated with ccRCC susceptibility or carcinogenesis, apolipoprotein C-I (APOC1), vascular endothelial growth factor A (VEGFA), scavenger receptor class B, member 1 (SCARB1) were found to be highly overexpressed in tumour tissue in both analysis." (PMID 23526956, 2013).
tumor (continued). "Bioinformatics analysis of 43 tumor samples from 14 HCC patients and 14 adjacent control tissues revealed that SPP1+ APOC1+ TAMs highly co-localize with CAFs, and SPP1 binds to ITGF1 secreted by CAFs, collectively remodeling the tumor immune microenvironment." (PMID 40764998, 2025). "In vivo experiments using nude mice demonstrated that APOC1 knockdown significantly reduced the expression of endothelial differentiation markers CD31 and VEGFA in tumor tissues." (PMID 39873475, 2025). "This aligns with evidence that high APOC1 expression enhances the secretion of cytokines, such as EGF, PDGF, VEGFA, IL-1, IL-8, TNF-α, MMP-9, MMP-2, and NO, which collectively drive tumor cell proliferation, invasion, and angiogenesis." (PMID 39873475, 2025). "Advanced techniques, such as immunofluorescence, TUNEL assay, and immunohistochemical labeling were employed to analyze the effects of APOC1 knockdown on the PI3K/AKT/mTOR signaling pathway and tumor formation in nude mice." (PMID 39873475, 2025). "APOC1 expression was higher in DLBCL cell lines (SU-DHL-4 and SU-DHL-8) compared to normal human B lymphocytes (GM2878), consistent with the tumor tissue data." (PMID 39873475, 2025). "Taken together, these findings suggest that knocking down APOC1 can promote apoptosis in DLBCL cells and reduce their proliferation, migration, invasion, angiogenesis, and tumor growth via the PI3K/AKT/mTOR signaling pathway." (PMID 39873475, 2025). "Bioinformatics analysis revealed that APOC1, CFH, LGALS1 and NUSAP1 were highly expressed in bone metastases compared to primary tumours, whereas ADRB2, NR4A2 and ZNF331 exhibited the opposite trend (p < 0.05)." (PMID 39098992, 2024). "Accumulated evidence revealed that LAMs shared a high expression of typical genes (such as APOE, APOC1, GPNMB, TREM2, SPP1 etc.)and played a central role in tumor immunity." (PMID 38346944, 2024). "High expression of CCL7, a natural antagonist for CCR5, demonstrates the role of APOC1+ TAMs in inhibiting the mobility of CD8+ T cells, thus suppressing tumor immune responses." (PMID 39232806, 2024). "The results showed that APOC1, CEP55, hsa-miR-378a, hsa-miR-145, and hsa-miR-504 were significantly differentially expressed in tumor tissues compared to normal tissues." (PMID 38172247, 2024). "In tumours, both AMɸ and AIMɸ upregulated genes involved in cholesterol and lipid transport and metabolism (such as ABCA1, APOC1, APOE, FABP3 and FABP5) compared to the background tissue." (PMID 38782901, 2024). "In the present study, we found that consistent with the findings on the role of APOC1 in other cancers, APOC1 also showed significantly higher expression in ESCA tissues than in normal tissues and tumor-adjacent tissues." (PMID 36969562, 2023). "APOC1+SPP1+ TAM secretes SPP1, which binds to ITGF1 secreted by CAFs to remodel the tumor microenvironment." (PMID 37333982, 2023). "Remarkably, in another module, the TIMP1 ligand secreted by CAFs bound to the receptor CD63 on the surfaces of tumor cells and TAMs, whereas the SPP1 ligand secreted by APOC1+SPP1+ TAM cells bound to the ITGB1 receptor on CAFs." (PMID 37333982, 2023). "The identified TYROBP→TREM2→A2M→APOE→APOC1 cascade is supported by the reports that TREM2 is expressed in tumor macrophages in over 200 human cancer cases and that there are interactions between TREM2/A2M, TREM2/APOE, A2M/APOE, and APOE/APOC1." (PMID 37129360, 2023). "A study found that APOC1, APOC2, APOC3, and APOC4 were expressed differently in tumor and non-tumor tissues in hepatocellular carcinoma." (PMID 38067270, 2023). "Mechanistically, ApoC1 induces EMT by activating STAT3, eventually promoting metastasis of the tumor." (PMID 36506554, 2022). "We validated five regulated alternative splicing events affected by PCBP1 using RT-qPCR and found that there was a significant difference in the expression of APOC1 and SPHK1 between tumour and normal tissues." (PMID 34857818, 2021).
tumor (continued). "Through co‐expression analyses, we verified that APOC1, ISG20 and SPP1 had notably strong correlations with tumour‐infiltrating immune cells, highlighting new directions for further research." (PMID 34498424, 2021). "As Chi-square analysis uncovered, APOC1 level was correlated to histological grade (P = 0.027) and TNM staging (P = 0.012) in RCC patients, whereas it was unrelated to age, gender, tumor size and histological subtypes." (PMID 33430855, 2021). "Notably, we established a novel six‐gene (APOC1, GLTP, ISG20, SPP1, SLC24A3 and UPP1) prognostic signature and discovered for the first time that this signature was associated not only with intrinsic aggressive features but also with the tumour immune microenvironment." (PMID 34498424, 2021). "Our study showed that APOC1 was highly expressed in RCC samples not only in a downloaded RCC profile, but also tumor tissues harvested from RCC patients." (PMID 33430855, 2021). "It appeared that APOC1 expressed at the highest level, followed by CYP2E1 and HPR in all tumor stages." (PMID 34081622, 2021). "Therefore, we speculated that APOC1 may act as an oncogene in ccRCC to promote tumor progression." (PMID 32974161, 2020). "Additionally, an in vivo study showed that APOC1 knockdown in nude mice reduced the expression of Ki67, CD31, and VEGFA in subcutaneous tumor tissues." (PMID 39873475, 2025). "Additionally, reducing APOC1 expression inhibited malignant growth of DLBCL cells and significantly suppressed tumor growth in mice." (PMID 39873475, 2025). "Therefore, APOC1+ TAMs and CXCL11+ TAMs potentially suppress anti-tumor immunity by inducing T cell dysfunction, exhaustion or even apoptosis through LGALS9 − HAVCR2 pair." (PMID 39232806, 2024). "Among them, the APOC1+ Mac subpopulation was a major component of HCC macrophage ecology compared to levels in adjacent control tissue, whereas the abundance of the FCN1+ Mac subpopulation was significantly decreased in tumor cells." (PMID 37333982, 2023). "Besides, significantly positive correlation between APOC1+APOE+ macrophages and CD163+ macrophages were analyzed in tumor nest." (PMID 36709495, 2023). "In our study, we found that SPP1 secreted by APOC1+SPP1+ TAM cells bound to ITGF1 secreted by FAP+ CAFs cells, suggesting that these two subpopulations may promote HCC development by remodeling the tumor microenvironment." (PMID 37333982, 2023). "Neither tumour size (P = 0.67) nor grade (P = 0.7) were significantly correlated with serum ApoC-1 concentration." (PMID 36381193, 2022). "According to the results of the present study, namely a poor correlation of ApoC1 serum levels to tumor volume and to immunohistologic staining intensity, the subset of neuroepithelial cells does not constitute an important source of circulating ApoC1 protein." (PMID 36216850, 2022). "Macrophage in this cluster had high expression of type I interferon signaling related genes (IFITM3, IFI27, MX1, IFI6, and ISG15) as well as gene features related to immunosuppressive phenotype (APOE, APOC1, S100A9, and GPNMB), whereby participating in tumor immune regulation." (PMID 35265520, 2022). "It is analyzed that APOC1 was upregulated in RCC tissues, especially advanced tumor cases." (PMID 33430855, 2021). "APOC1 is primarily expressed in tumor cells and macrophages and shows a positive correlation with the expression of genes such as CD68, CD86, CD163, CXCL17, CXCL8, and IL-10, suggesting that APOC1 may promote tumor progression by influencing macrophage polarization." (PMID 39877420, 2024). "Combined with the results of correlation analysis of APOC1 expression with target molecules, immune-related molecules, and inflammatory chemokines, AOPC1 may be involved in immune infiltration and inflammatory responses in the tumor microenvironment and tumorigenesis and development." (PMID 36969562, 2023).
tumor (continued). "The main limitation of this study was the evaluation of ApoC-1 in the serum and tumour tissue of the same patients which could potentially enable us to hypothesize whether OSCC tissue expresses and secretes ApoC-1 in the serum or not." (PMID 36381193, 2022).
cancer (57 papers, 2008 to 2025). A tumor composed of atypical neoplastic, often pleomorphic cells that invade other tissues. "Recent investigations suggest that APOC1 is a potential therapeutic target as well as a valuable diagnostic, prognostic, and immune biomarker for various cancers." (PMID 39873475, 2025). "Increasing evidence indicates that APOC1 is overexpressed in various cancers and is significantly associated with poor patient prognosis." (PMID 39877420, 2024). "First, the mutation and amplification of APOC1 rank as the sixth highest in OV compared to pan-cancer." (PMID 38515073, 2024). "Recent studies have demonstrated that APOC1 is associated with cancer progression, exerting cancer-promoting and immune infiltration-promoting effects." (PMID 38515073, 2024). "Recent studies in humans have shown that APOC1 may associate with the development of cancers." (PMID 35765478, 2022). "Apolipoprotein C1 (APOC1) plays a significant role in the proliferation and metastasis of various malignant tumors; however, its role in DLBCL—particularly its effects on angiogenesis—remains largely unexplored." (PMID 39873475, 2025). "APOC1+ TAMs also exhibited high expression level of SPP1, a key gene in macrophage polarization linked to poor prognosis for cancer." (PMID 39232806, 2024). "We further investigated the effects of APOC1-silenced macrophages on cancer cells by employing a co-culture system with the MDA-MB-231 and MDA-MB-468 cell lines." (PMID 39877420, 2024). "PDE4C and APOC1 were predicted as key mediators for the crosstalk between M2 macrophage and cancer cells." (PMID 38774995, 2024). "For example, ApoC1 is found to promote breast tumorigenesis by altering cell adhesion and migration processes, while ApoM has inhibitory effects on cancer cell invasion and proliferation, potentially by its interaction with vitamin D receptors." (PMID 39744067, 2024). "APOC1 is also closely related to the infiltration of various immune cells in various cancers, indicating that this macrophage subtype also has potential immune regulatory functions." (PMID 39192976, 2024). "The IHC research revealed elevated expression of APOC1 in IgAN kidney tissue using normal kidney tissue from cancer as a control group." (PMID 37305534, 2023). "We stimulated CRC cancer cells with TAM supernatant in order to further confirm the function of APOC1 in CRC TAMs in vitro." (PMID 36908705, 2023). "Apolipoprotein C1 (APOC1) is a member of the apolipoprotein family that participates in lipoprotein metabolism and cancer development." (PMID 37576389, 2023). "We anticipate publishing more information about the connection between APOC1 function and cancer in many cell types." (PMID 36908705, 2023). "Knockdown of the APOC1 gene can inhibit cancer progression, which indicates that ApoC1 has the potential to be a target for diagnosis and therapeutics." (PMID 36506554, 2022). "In the progression of GBM, cancer cell proliferation, migration, and invasion are promoted due to the overexpression of ApoC1." (PMID 36506554, 2022). "In vitro, ApoC1 promotes not only cancer cell proliferation but also migration and invasion via inducing EMT." (PMID 36506554, 2022). "Through literature review, APOC1 has been identified as a promising serum marker for human cancers, which is conductive to cancer diagnosis and treatment." (PMID 33430855, 2021). "By means of TWAS, we recovered seven genes (APOC1, APOE, BIN1, HMGB1, PRKAA1, SQSTM1, and UCP2) significantly associated to AD traits and some cancer models." (PMID 31608105, 2019). "An earlier study reported that apoC1 purified from HDL was responsible for the mitogenic effect of HDL on bovine vascular endothelial cells in vitro and, in the recent years, apoC1 emerged as a molecule involved in cancer progression." (PMID 31779116, 2019).